IL1B (interleukin 1 beta)
Diseases named in the same sentence as IL1B in open-access papers (continued):
Sharing a sentence is not in itself a finding about the gene and the disease.
Sepsis (continued). "The inconsistent reports of TNFα and IL-1β concentrations in neonatal sepsis may be a confounded by the kinetics and short half-life of circulating TNFα and IL-1β and the timing of sample collection relative to the onset of sepsis." (PMID 30555806, 2018). "Interestingly, exosomal miR-146a contributes to the enhanced therapeutic efficacy of IL-1β-primed mesenchymal stem cells against sepsis." (PMID 30337925, 2018). "Furthermore, IL-1β inhibits the β-adrenergic agonist-mediated increase in cAMP and cardiomyocyte contractility and IL-1β is an essential mediator in sepsis-induced contractile dysfunction." (PMID 29695980, 2018). "Although this strategy may initially benefits the host, it soon starts a vicious circle of pyroptotic release of IL-1β and additional DAMPs that may lead to death, as it occurs in sepsis or toxic shock." (PMID 30352992, 2018). "The results of an in vitro (lipopolysaccharide (LPS))-stimulated experiment showed that this sepsis-associated high-risk AA genotype significantly increased IL-27 levels and enhanced TNF-α and IL-1β production in the peripheral blood mononuclear cells (PBMCs) upon exposure to LPS in vitro." (PMID 30268141, 2018). "Interestingly, JMJD3 expression levels in neutrophils were increased and contributes to the production of pro-inflammatory IL-1β in early sepsis." (PMID 30337925, 2018). "Our present study differed from previous investigations using the animal models induced by stress, LPS or sepsis, where we directly determined hippocampal cytosol protein levels of IL-6, IL-1β, and TNF-α by using acute and chronic ketamine administration models." (PMID 28373844, 2017). "Nlrp3 knockout mice showed reduced IL-1β serum levels in sepsis." (PMID 28097512, 2017). "This study demonstrates an association between significant cardiac depression by SE and increase in expression of pro-inflammatory cytokines (TNF-α, IL-6, and IL-1β) further supporting the current literature regarding the role of pro-inflammatory cytokines in the development of myopathy in sepsis." (PMID 28405943, 2017). "Anti-inflammatory effects of LPC, including a reduction of peritoneal IL-1β levels, were reported for experimental sepsis in the mouse and these effects seemed to depend on the presence of 18 carbon molecules in the acyl chain, whereas we used LPC with a chain length of 16 in our experiments." (PMID 28725182, 2017). "Interleukin-1β (IL-1β) is one of the most activated cytokines in sepsis." (PMID 28097512, 2017). "However, IL-1β is only one of many cytokines that are elevated during the cytokine storm in the acute phase of sepsis." (PMID 28097512, 2017). "Likewise, decreased activation of IL-1β in Nlrp3 KO mice during sepsis resulted in decreased Il6 expression, which is a target of IL-1β and mediates atrophy." (PMID 28097512, 2017). "Another recent study confirmed that IL-1β is involved in cognitive impairment after sepsis in rats, showing that IL-1β may be involved in brain dysfunction." (PMID 28373844, 2017). "Based on these observations, it is possible that Nlrp3 KO mice have less overall inflammation during sepsis when compared to Nlrp3 WT animals and that not only decreased IL-1β levels but also reduced overall inflammation contributed to reduced muscle atrophy in septic Nlrp3 KO mice." (PMID 28097512, 2017). "The failure of anti-TNF-α- or IL-1β-based therapies to decrease the death toll in sepsis patients has generated doubts as to whether cytokine-based treatments can be effective." (PMID 28533774, 2017). "Activation of the innate immune system by sepsis produces pro-inflammatory cytokines (TNFα, IL-1β and IL-6) that may trigger muscle wasting." (PMID 28883493, 2017). "Therefore, in the initial phase of sepsis, the anti-inflammatory therapy is effective and blocking the activity of IL-1β with biologic inhibitors has been used to prevent sepsis but showed limited effectiveness." (PMID 29375379, 2017).
Sepsis (continued). "In addition to the measurement of IL-1Ra, the serum levels of TNF-α and IL-1β, two key proinflammatory cytokines involved in the LPS-sepsis, were also quantified." (PMID 28383060, 2017). "The elevatedexpression of TNF-α, IL-1β, and IL-6 is an important step in the pathogenesis of ALI andacute respiratory distress syndrome.Moreover, in the case of humans with ALI or sepsis, a persistent elevation of thesecytokines was associated with a poor prognosis." (PMID 26648090, 2016). "A previous study revealed that over-expression of PPARβ/δ could attenuate gene expression of TNFα, IL-1β and IL-6 in alveolar macrophages and played a protective role in sepsis-induced acute lung injury." (PMID 27023591, 2016). "Also, IL-1β has been found to be detectable in only a small proportion of patients with systemic inflammatory response syndrome and sepsis." (PMID 27059056, 2016). "Cytokines (TNF-α and IL-1β) might play key roles in the early decrease in contractility, but they cannot explain the prolonged myocardial dysfunction in sepsis because the effect of TNF-α is maximal between 8 and 48 h after administration." (PMID 27011791, 2016). "These waves of cytokine gene activation, short for IL-1β and prolonged for IL-8 until 12 h, are supported by data of DeForge and Remick that studied the kinetics of these cytokines in LPS-stimulated human whole blood as an ex vivo model of sepsis." (PMID 27619959, 2016). "The animals 18 h after CLP-induced sepsis had marked elevations in IL-1β, IL-6, TNF-α, and MCP-1." (PMID 27822777, 2016). "We assessed expression of a panel of genes reported to be highly upregulated during CLP sepsis, including tnfa (tumor necrosis factor α) and il1b (interleukin 1 beta), which were undetectable in the CNS in any condition despite marked upregulation in the liver following CLP (data not shown)." (PMID 26790027, 2016). "In addition, CSE gene deletion not only attenuated sepsis associated activation of ERK1/2-NF-κB p65 signalling but also abolished the generation of cytokines TNF-α, IL-6, and IL-1β and chemokines MCP-1 and MIP-2α." (PMID 27518439, 2016). "The ability of insulin to suppress LTB4 and IL-1β production is in tune with the previous suggestion that insulin has anti-inflammatory actions and its infusion may be of benefit in sepsis and ARDS." (PMID 27887602, 2016). "This failure may beexplained by the fact that the levels of TNF-α and IL-1β are elevated during the earlystage of sepsis and recover at the late stage of disease." (PMID 26648090, 2016). "Proinflammatory cytokines TNF-α, IL-1β, and IL-6 are produced in the initial phase of sepsis." (PMID 27195281, 2016). "TNF-α, IL-6, and IL-1β are the main inflammatory cytokines released in sepsis, which may assess the severity of sepsis." (PMID 26904148, 2016). "Furthermore, the sepsis-induced increases in tissue levels of IL-1β, IL-6, and TNF-α mRNAs were lowered when the two blockers were given together to the animals." (PMID 27822777, 2016). "Rhein could significantly decrease concentration of serum urea and creatinine and level of TNFα, NFκB, and IL-1β in two different mouse models of experimental sepsis." (PMID 26904117, 2016). "Furthermore, compared to the inflammatory response typically related to exercise, severe inflammation (e.g., sepsis) has been associated with a distinctively different cascade of cytokines in the circulation (i.e., TNF-α, IL-1β and IL-6 in that order)." (PMID 26378783, 2015). "TNF-α and IL-1β are the most intensively studied inflammatory mediators of pathology in sepsis." (PMID 26440998, 2015). "In this study, two polymorphisms (IL-1β (−511) and IL-1R) were significantly associated with the development of MOF and mortality where as IL-1α (−889) polymorphism was associated with susceptibility for sepsis." (PMID 26561011, 2015).
Sepsis (continued). "In conclusion, our study demonstrates that the alternations in the genotype and allele frequency of IL-1β (−511C/T), TNF-α (−308G/A), TNF-α (−238G/A) and IL-10(−1082G/A) genes are associated with an increased risk of sepsis development in major trauma patients and outcomes." (PMID 26561011, 2015). "In this study, two polymorphisms (IL-1β (−511) and IL-1R) were significantly associated with the development of MOF and mortality, where as IL-1α (−889) polymorphism associated with susceptibility for sepsis." (PMID 26561011, 2015). "In our recent work, we demonstrated that stefin B-deficient mice were significantly more sensitive to the lethal lipopolysaccharide (LPS)-induced sepsis, due to increased caspase-11 expression and secreted higher amounts of pro-inflammatory cytokines IL-1β and IL-18." (PMID 26696823, 2015). "Rhein could significantly decrease concentration of BUN and SCr and level of TNF-α and IL-1β in two different mouse models of experimental sepsis." (PMID 26149595, 2015). "Sequence-specific primer based PCR indicated that eight polymorphic loci IL-1α /-889, IL-1β/-511, IL-1R (pstI 1970), TGF-β/ code 10, TNF-α/-308, TNF-α/-238, IL-6/+565 and IL-10/-1082, out of 22 SNPs are significantly associated with sepsis morbidity and outcome." (PMID 26561011, 2015). "However, the excessive cytokine levels seem to stage for tissue injury and organ failure, and high levels of IL-1β correlates with severity and mortality of sepsis." (PMID 25400921, 2014). "STNFR1, STNFR2, adiponectin and IL-1β were associated with delirium, but sepsis did not modify the relationship between these biomarkers and delirium occurrence." (PMID 24886875, 2014). "Our meta-analysis indicated that IL-1A-889, IL-1B + 3954 and IL-1RN VNTR might be associated with sepsis susceptibility." (PMID 24428862, 2014). "Hence, the caspase-1 function in sepsis was independentof processing and releasing IL-1β and IL-18, in spite of having reducedlevels of serum IL-1β, IL-18 and IL-6 incaspase-1−/− mice during sepsis." (PMID 25412304, 2014). "The acetylcholinesterase inhibitor neostigmine, which enhances cholinergic signaling by increasing acetylcholine levels, improved survival and reduced cytokine levels of TNF-α and IL-1β and attenuated neutrophil lung infiltration in a cecal ligation and puncture sepsis model." (PMID 25139304, 2014). "Removal of each study did not seem to alter the relationships with sepsis risk and heterogeneity for IL-1B-511 and −31, suggesting the reliability of these results." (PMID 24428862, 2014). "Furthermore, the previous study showed that proinflammatory mediators, such as tumor necrosis factor-α (TNF-α) and interleukin-1β (IL-1β), played a critical part in myocardial dysfunction during sepsis." (PMID 24959004, 2014). "However, whereas SNPs in the IL1β and in MMP-16 genes were associated with an increased risk of sepsis, variations of BPI and DEFβ1 seemed to play a protective role." (PMID 25000179, 2014). "Furthermore, in patients with sepsis, caspase-1 levels are significantly decreased, and the inhibition of caspase-1 and defective IL-1β production constitute an important immunological feature of sepsis." (PMID 24098117, 2013). "In addition, levels of several inflammatory cytokines (TNF-α, IL-10, IL-1β), described as markers of sepsis, were reduced in galectin-3−/− mice." (PMID 23527230, 2013). "Next, to determine whether NOD2-mediated IL-1β and IL-10 production plays a critical role in C5a generation during sepsis, we administered rIL-1β or rIL-10 to WT or Nod2−/− mice 4 h or 12 h after CLP, respectively." (PMID 23675299, 2013). "However, our experiments demonstrated that the levels of IL-6 and TNF-α in serum and peritoneum, and cytosolic IL-1β and IL-10 expression in macrophages were similar between WT and Nod2−/− mice during sepsis." (PMID 23675299, 2013). "Therefore, it is feasible that NOD2-mediated signals induce IL-1β and IL-10 production by immune cells during sepsis." (PMID 23675299, 2013).
Sepsis (continued). "IL1β, IL-6, and TNFα are believed to play a central role in sepsis-mediated myocardial depression." (PMID 23691359, 2013). "As TNF-α and IL-1β mediate most of the physiological disturbances which are characteristic for sepsis, it is possible that the down-regulation of PNoc and NOP in peripheral blood cells might restrict the production of pro-inflammatory cytokines." (PMID 24066107, 2013). "To test this hypothesis, we attempted to suppress pro-inflammatory gene activity in RAG−/− mice by blocking TNF signaling with a neutralizing antibody, which has been shown to decrease IL-1β production in models of sepsis and arthritis." (PMID 24130499, 2013). "Furthermore, studies have shown that levels of TNF-α, IL-1β, and IL-6 are markedly increased in patients with established sepsis." (PMID 22655058, 2012). "There is overwhelming support for increased IL-1β expression in severe sepsis." (PMID 21939530, 2011). "Inhibition of IL-1β in sepsis was more profound than tumour necrosis factor (TNF)." (PMID 21244670, 2011). "IL-1β is a major component of the pro-inflammatory response during sepsis." (PMID 21244670, 2011). "As a consequence, production of IL-1β when sepsis appears may be modulated either at the level of gene transcription or at the level of cleavage of pro-IL-1β." (PMID 21244670, 2011). "On the other hand, caspase-1 activation of IL-1β and IL-18 also represents protective host defense mechanisms, and their inactivation may well be an important component of immunoparalysis in sepsis." (PMID 21244670, 2011). "Previous studies have demonstrated that proinflammatory cytokines play a critical role in the initiation and progression of sepsis syndrome and that TNF-α, interleukin (IL)-1β, and IL-6 are important mediators of hemodynamic, metabolic, and immunologic alterations in the host during sepsis." (PMID 18680601, 2008). "Previous studies have demonstrated that proinflammatory cytokines play a critical role in the initiation and progression of sepsis syndrome and that TNF-α, IL-1β, and IL-6 are important mediators of hemodynamic, metabolic, and immunologic alterations in the host during sepsis." (PMID 18680601, 2008). "We compared cytokine concentrations among patients with severe sepsis and septic shock, and observed that concentrations of IL-1β, IL-6, IL-7, IL-8, IL-10, IL-13, IFN-α, MCP-1 and TNF-α were significantly increased in septic shock as compared with severe sepsis." (PMID 17448250, 2007). "Data indicate that SNPs of TNF-α, Il-1β, PAI-1, and CD14 may be associated with a poor prognosis from sepsis." (PMID 17877801, 2007). "In our study, the serum TNF-α and IL-1β levels were significantlyincreased in newborns with sepsis." (PMID 18274637, 2007). "Thus, it is plausible that LIPUS combined with IMI may exert a protective role during the early stages of sepsis by downregulating IL‐1β expression and inhibiting the NF‐κB signaling pathway." (PMID 41551210, 2026). "Therefore, the effects of IL-1β on sepsis remain to be further determined." (PMID 39927458, 2025). "In addition, qPCR results showed that the mRNA levels of GSDMD, IL‐1β, caspase‐1, and caspase‐11 in liver tissues were significantly increased in LPS‐ and CLP‐induced sepsis models, and the serum concentration of IL‐1β in the sepsis model was also significantly increased." (PMID 40856013, 2025). "Consequently, these findings indicated that the elevated expression of hub genes in IL1B+ macrophages in IBD may contribute to the progression of sepsis patients through an inflammatory factor storm." (PMID 39993996, 2025). "Moreover, a low dose of DEX could increase glucocorticoid receptor-α levels and decrease plasma levels of TNF-α and IL-1β in the kidney, alleviating sepsis-induced kidney injury." (PMID 40872555, 2025).
Sepsis (continued). "Abnormal activation of the inflammatory body NLRP3 is associated with many inflammatory diseases, and sepsis-triggered typical inflammasome depends on the NLRP3/caspase-1 pathway to mature and secrete IL-1β, which may lead to the reduced generation of new neurons." (PMID 40218223, 2025). "Conversely, other studies have demonstrated that lactic acid may partially restore PGC-1α activity, reduce the expression of pro-inflammatory cytokines including TNF-α, IL-1β, and IL-6, alleviate renal injury, and improve survival in murine models of sepsis-induced AKI." (PMID 40843128, 2025). "Sepsis patients with a history of severe COVID-19 exhibited elevated IL-6, IL-1β, and IL-17 levels, prolonged APTT, and increased 28-day mortality, indicating that past severe COVID-19 infection may contribute to systemic inflammation and coagulation disturbances, further worsening prognosis." (PMID 41305706, 2025). "Our results show that CLP-sepsis resulted in a rise in the cardiac phosphorylation of IKK and, hence, activation of NF-κB pathway, which was associated with an increased expression of NLRP3 in the heart and augmented systemic release of the cardio-suppressive IL-1β." (PMID 39559354, 2024). "Sepsis (sepsis) is a systemic inflammatory response triggered by infection, and its pathologic features include overproduction of peripheral inflammatory factors (e.g., IL-1β, IL-6, TNF-α), which ultimately leads to cytokine storm and multiple organ dysfunction syndrome (MODS)." (PMID 39720715, 2024). "Furthermore, the consequences of CKD, including sepsis, fibrosis, and accelerated vascular calcification, may be influenced by the IL-1β/IL-18 axis." (PMID 38449859, 2024). "Additionally, our investigation revealed that intervention with BBR could diminished the activation of NF-κB signaling in myocardial cells and decreased the expression levels of TNF-α and IL-1β in myocardial tissues of sepsis rats." (PMID 39568588, 2024). "Moreover, network pharmacology indicated that oxidative stress and inflammation are associated with sepsis-induced ALI; therefore, we detected the expression of oxidative stress factors (MPO, ROS, MDA, and SOD) and inflammatory factors (TNF-α, IL-6, and IL-1β) in LPS-stimulated HUVECs." (PMID 38445620, 2024). "Therefore, the elevation of IL-1β and IL-18 secretion by infected monocytes may contribute, at least in part, to sepsis observed in melioidosis patients." (PMID 39042701, 2024). "It has been observed that sepsis-induced endothelial cell activation escalates systemic inflammatory markers such as IL-1β, IL-6, and TNF-α, as well as the production of reactive oxygen species, factors that may accelerate the onset of sepsis-associated delirium (SAD)." (PMID 38357643, 2024). "Although RIC has been shown to lower levels of IL-6, TNF-α, and IL-1β and improve survival in animal models of sepsis, whether this concept inspired by animal studies has an impact on inflammatory cytokines stimulated by COVID-19 has not been previously explored." (PMID 36445625, 2024). "In humans with sepsis, circulating depressing factors, such as IL-1β, are speculated to induce myocardial dysfunction, and cardiac dysfunction after inflammation is further evidenced in human fetuses exposed to pre-labor rupture of membranes (PROM) or i.a. infections." (PMID 36994431, 2023). "miR-25-5p can improve brain injury caused by sepsis by inhibiting the thioredoxin-interacting protein TXNIP/NLRP3 pathway; reducing the levels of TXNIP, NLRP3, and cleaved caspase-1; and inhibiting the expression of inflammatory factors (such as IL-6, IL-1β, and TNF-α and peroxide)." (PMID 37629199, 2023). "This sepsis-induced immunosuppression is typically characterized by dysfunctional monocytes, which show a decreased release of pro-inflammatory cytokines such as tumor necrosis factor α (TNFα), IL-1β and IL-6 upon stimulation with LPS and an enhanced secretion of anti-inflammatory IL-10." (PMID 37759239, 2023).